ENSG00000285982 (novel protein)
Gene: Protein-coding gene on chromosome 8 (103,398,658 to 103,501,895, reverse strand). Ensembl gene ENSG00000285982.
Genetic constraint (gnomAD): Loss-of-function variants: 17 observed, 25.1 expected, observed/expected ratio (o/e) 0.68, 90% interval 0.46 to 1.02. Missense variants: 227 observed, 276.05 expected, observed/expected ratio (o/e) 0.82, 90% interval 0.74 to 0.92. Synonymous variants: 101 observed, 100.92 expected, observed/expected ratio (o/e) 1, 90% interval 0.85 to 1.18.